IL6 (interleukin 6)
Diseases named in the same sentence as IL6 in open-access papers (continued):
Sharing a sentence is not in itself a finding about the gene and the disease.
periodontitis (continued). "They determined that LRG1 levels in serum and periodontal tissue are elevated in periodontitis and contribute toperiodontal tissue damage via interleukin-6 production." (PMID 40822769, 2025). "A study conducted in 2024 associated high values of IL-6 and IL-17 in GCF with the presence of severe and advanced periodontitis, suggesting a possible diagnostic role of the cytokines in comparing different stages and grades of periodontitis." (PMID 41149097, 2025). "Biochemical analysis revealed significantly elevated salivary IL-6 levels in the periodontitis group (71.76 ± 7.54 ng/L) compared to the healthy group (25.07 ± 5.28 ng/L; p < 0.001)." (PMID 41007333, 2025). "Patients with periodontitis also exhibit elevated serum levels of IL-6 and CRP, with IL-6 levels correlating with the severity of the disease." (PMID 39852378, 2025). "In periodontitis, particular focus has been placed on SNPs in genes regulating key pro-inflammatory cytokines—such as IL-1, IL-6, and TNF-α—as well as those involved in Toll-like receptor (TLR) signaling and matrix metalloproteinase (MMP) activity." (PMID 40869939, 2025). "When P. gingivalis is present, peripheral CD4+ T helper cells produce more proinflammatory cytokines, such as interleukin-1 and interleukin-6, which promote the development of severe periodontitis." (PMID 40692535, 2025). "Compared with T2DM patients with healthy periodontal conditions, T2DM patients with periodontitis exhibit significantly higher expression of ferroptosis-related genes, such as IL-1β, IL-6, NFE2L2, and ALOX5, in pancreatic tissue." (PMID 40541947, 2025). "In addition, it is plausible that IL-6 concentrations fluctuate between acute flare-ups and chronic stable phases of periodontitis, which may influence its temporal diagnostic utility and should be taken into account when interpreting salivary levels across different clinical contexts." (PMID 41007333, 2025). "Tumor necrosis factor alpha (TNF-α), interleukin-1 beta (IL-1β), and interleukin-6 (IL-6) are critical cytokines in the etiology of periodontitis." (PMID 40564062, 2025). "In contrast, visfatin and IL-6 levels were significantly elevated in the periodontitis group when compared to both the gingivitis and control groups (p = 0.000 for both)." (PMID 41280712, 2025). "Cytokines, including TNF-α, CRP, IL-6, IL-17, IL-8 and IFN-γ, are associated with periodontitis and gestational diabetes mellitus." (PMID 41394354, 2025). "Studies have also shown that genistein significantly reduced the expression levels of TNF‐α, IL‐6, IL‐1β, and IL‐17a in the gingival tissue of periodontitis mice and reduced the damage of inflammatory factors to periodontal tissue." (PMID 40761494, 2025). "Difficulty chewing often stems from oral infections such as periodontitis, which release pro-inflammatory cytokines like IL-6 and TNF-α." (PMID 41181690, 2025). "We identified a pro-inflammatory signature in GCF of T1DM individuals with periodontitis, marked by elevated IL-1β, IL-6, IL-8, and IL-17A, suggesting activation of both innate and adaptive immune pathways." (PMID 41280935, 2025). "Repeatedly elevated inflammatory markers, including IL-6, TNF-α, and CRP, as well as regulatory T-cells, were observed in individuals with periodontitis, indicating a potentially shared pathogenic environment with certain tumors." (PMID 41384174, 2025). "Pro-inflammatory cytokines such as IL-1β, IL-6, and IL-8 in the environment of periodontitis stimulate neutrophils to transition into a more aggressive and pro-inflammatory state." (PMID 40370404, 2025). "Compared to the Experimental Periodontitis (EP) group, both inhibitors significantly downregulated the mRNA expression of Il‐6, Tnf‐α, and Rankl, and also reduced TNF‐α protein levels in gingival tissues." (PMID 41041963, 2025). "Salivary IL-6 and irisin levels were significantly elevated in periodontitis patients compared to controls (p < 0.001)." (PMID 41007333, 2025).
periodontitis (continued). "These receptors are known to mediate anti-inflammatory responses by inhibiting the production of pro-inflammatory cytokines such as TNF-α, IL-6, and NF-κB, which are central to the pathogenesis of periodontitis." (PMID 40256760, 2025). "This study demonstrated that salivary irisin and IL-6 concentrations were significantly elevated in individuals with Stage 3 Grade C periodontitis, aligning with clinical indicators of periodontal destruction such as PD, CAL, and BOP." (PMID 41007333, 2025). "Among them, IL-1β and IL-6 have shown particular promise in distinguishing between health, gingivitis, and periodontitis." (PMID 41155385, 2025). "A significant increase in both irisin and IL-6 levels was observed in the periodontitis group compared to healthy controls." (PMID 41007333, 2025). "For instance, increased systemic inflammatory markers, such as C-reactive protein (CRP) and IL-6, are commonly elevated in both periodontitis and these systemic conditions, suggesting shared pathological mechanisms." (PMID 40066344, 2025). "From healthy to severe periodontitis, the expression of IL-1β, IL-6, IL-8, TNF and MMP-9 gradually increased, but the E–P interaction scores remained constant, suggesting a persistent epigenetic regulatory footprint." (PMID 40902506, 2025). "Typically, IL-6 and TNF-α were positively associated with bone destruction and inflammation of periodontitis; blood CTXI and PINP serve as markers of bone resorption and bone formation, respectively." (PMID 41154794, 2025). "In the immune response to periodontitis, dendritic cells infected by Pg activate related SASPs, such as IL-1β, IL-6, and IL-8, which ultimately accelerate the progression of periodontitis." (PMID 40801798, 2025). "Boxplot visualizations provide a clear comparison of salivary IL-6 and irisin concentrations between the periodontitis and healthy control groups." (PMID 41007333, 2025). "Salivary irisin levels were reduced in individuals with gingivitis and periodontitis, whereas visfatin and interleukin-6 levels were elevated." (PMID 41280712, 2025). "To explore the mechanistic role of PIEZO1 in TO-associated periodontitis progression, we performed immunohistochemistry (IHC) staining to analyze the expression of PIEZO1, interleukin (IL)-6, and runt-related transcription factor 2 (RUNX2) in PDL tissue." (PMID 41234768, 2025). "IL6 is one of the most potent proinflammatory cytokines and is involved in the periodontitis occurrence in human gingival fibroblasts cultured in vitro." (PMID 40004956, 2025). "This ferroptosis induction leads to an increase in the levels of proinflammatory cytokines, including IL-1β, IL-6, and IL-8, thereby exacerbating the progression of periodontitis." (PMID 40541947, 2025). "This inflammatory response manifests through substantial elevations in interleukin-1 beta (IL-1β), tumor necrosis factor-α (TNF-α), and interleukin-6 (IL-6) in periodontitis patients." (PMID 40869031, 2025). "This is the first study to integrate clinical, biochemical, and in silico analyses of salivary irisin and IL-6 in Stage 3 Grade C periodontitis." (PMID 41007333, 2025). "This study demonstrated significantly higher salivary concentrations of visfatin and interleukin-6 (IL-6) in patients with gingivitis and periodontitis relative to periodontally healthy controls." (PMID 41280712, 2025). "The pro-inflammatory cytokines (IL-1, IL-6, and TNF-α) have been implicated in stimulating osteoclastic resorption in periodontitis." (PMID 41289041, 2025). "For example, the concentrations of Aβ, lactoferrin, and IL-6, and the relative abundance of Porphyromonas gingivalis in the saliva of periodontitis patients, increased when compared with those of healthy controls." (PMID 40076682, 2025). "Periodontitis induces a local and systemic inflammatory response, with an increase in pro-inflammatory cytokines such as IL-1β, IL-6, and TNF-α." (PMID 40231144, 2025).
periodontitis (continued). "The present study aimed to investigate the diagnostic potential and biological relevance of two salivary biomarkers, IL-6 and irisin, in individuals with Stage 3 Grade C periodontitis." (PMID 41007333, 2025). "The role of inflammation in periodontitis is well-documented, with cytokines such as IL-6 and TNF-α playing central roles in disease progression." (PMID 40085302, 2025). "Several studies have shown that levels of IL-1β, IL-6, IL-8, and IL-17A are elevated in periodontal tissues of patients with periodontitis compared to healthy controls, driving disease progression." (PMID 41274884, 2025). "Macrophage polarization critically influences periodontitis progression: pro-inflammatory M1 macrophages exacerbate bone resorption through IL-6 and TNF-α secretion, whereas anti-inflammatory M2 macrophages facilitate tissue repair via cytokines such as IL-10." (PMID 41124423, 2025). "The concentration of IL-6 in serum, saliva, and gingival fluid was higher in patients with periodontitis than in healthy subjects." (PMID 40002575, 2025). "We found that both interleukin-6 and irisin levels were higher in individuals with advanced periodontitis compared to healthy individuals." (PMID 41007333, 2025). "In obese patients, adipose cells and macrophages within adipose tissue secrete TNF-α and IL-6; these adipocytokines play a pivotal role in the link between obesity and periodontitis." (PMID 41328144, 2025). "Collectively, periodontitis contributes to the incidence of AF, possibly by upregulating the circulating levels of IL-6 and immune responses." (PMID 40894185, 2025). "In a recent publication, it was described that salivary IL-6 levels are significantly higher in periodontitis stage III/IV compared with those in stage I/II or controls without advanced periodontal disease." (PMID 40809956, 2025). "Significantly elevated serum levels of TNF-α and IL-6 were detected in the Experimental Periodontitis (EP) group, with significant differences compared to the Negative Control (NG) group." (PMID 40649395, 2025). "IL-8 is elevated in the gingival tissue of periodontitis patients, and both IL-6 and IL-8 are potential biomarkers for oral and oropharyngeal squamous cell carcinoma." (PMID 40771401, 2025). "Although the frequency of periodontitis was similar in all groups, higher IL-6 (p = 0.004), IL-1β (p = 0.002), and IL-33 (p = 0.006) levels were associated with poor periodontal status." (PMID 40008732, 2025). "One of the primary outcomes is the suppression of pro-inflammatory cytokines, such as TNF-α, IL-6, and NF-κB, which are downregulated, thereby reducing tissue destruction and limiting the progression of periodontitis." (PMID 40256760, 2025). "Peripheral neutrophils from patients with periodontitis release increased amounts of IL-1β, IL-8, IL-6, and tumor necrosis factor (TNF)-α upon stimulation with periodontal pathogens." (PMID 40572711, 2025). "The observed elevation of IL-6 and irisin levels in periodontitis patients, along with their strong correlations with key clinical parameters, highlights their potential utility in non-invasive disease detection and monitoring." (PMID 41007333, 2025). "Its anti-inflammatory properties help lower the levels of pro-inflammatory cytokines such as TNF-α, IL-1β, and IL-6, which are crucial in driving tissue damage in periodontitis." (PMID 40530190, 2025). "CEA expression has been shown to be regulated by IL-6 via trans-signalling mechanisms – a key cytokine elevated in periodontitis and related to BOP levels." (PMID 40451975, 2025). "Periodontitis acts as a chronic source of IL-6, which, besides promoting periodontal tissue destruction, has been linked to the development and progression of CRC." (PMID 40944094, 2025). "This dual modulation supports GLP-1RAs as a potential adjunctive anti-inflammatory therapy in periodontitis by suppressing cytokines such as IL-6, IL-1β, and TNF-α." (PMID 41328144, 2025).
periodontitis (continued). "The ELISA results showed the NF-κB signaling related inflammatory cytokines such as TNFa, IL-1β, and IL-6 increased in the Bmal1- periodontitis group." (PMID 40008712, 2025). "In this study, we observed marked upregulation of TNF-ɑ and IL-6 mRNA expression in the P-UC group, indicating an amplified inflammatory response in the presence of periodontitis." (PMID 40462053, 2025). "The study also showed significant upregulation of inflammatory cytokines such as IL-6, IL-8, and IL-18 in response to LPS from E. coli, highlighting its relevance for studying early stages of periodontitis." (PMID 39963082, 2025). "The literature consistently indicates that individuals with periodontitis exhibit significantly higher IL-6 levels compared to healthy individuals, emphasizing its contribution to disease progression." (PMID 41007333, 2025). "Elevated IL-6 is a pathway that links periodontitis with diabetes, coronary heart disease, and COPD." (PMID 41463036, 2025). "Elevated systemic IL-6 levels have been observed in patients with periodontitis, linking local oral inflammation to broader inflammatory burden in the body." (PMID 41155385, 2025). "By integrating cortisol with staging and grading of periodontitis and concurrently evaluating IL-1β and IL-6, we offer new insights into the complex biological underpinnings of stress-related periodontal pathology." (PMID 40843742, 2025). "In this in silico analysis, we investigated the potential molecular pathways and targets associated with IL-6 and irisin, two biomarkers significantly elevated in Stage III Grade C periodontitis." (PMID 41007333, 2025). "In the present study, IL-6 concentrations were approximately three times higher in the periodontitis group compared to the healthy group, in agreement with previous findings." (PMID 41007333, 2025). "While our findings demonstrate a significant reduction in IL-6 and TNF-α in the CO group, these two markers represent just a fraction of the inflammatory processes underlying periodontitis." (PMID 40085302, 2025). "In contrast, gingivitis and periodontitis reported elevated levels of visfatin and interleukin-6 compared to the control group (p < 0.05)." (PMID 41280712, 2025). "Our study aimed to determine salivary irisin, visfatin, and interleukin-6 levels in gingivitis and periodontitis patients, compare them with healthy periodontal patients, and evaluate the association between these biomarkers." (PMID 41280712, 2025). "In this study, we focused on IL-1β and IL-6, which are central inflammatory mediators in periodontitis, to provide a representative assessment of the inflammatory response alongside salivary cortisol." (PMID 40843742, 2025). "Increased IL-6-specific mRNA levels in mononuclear cells of the gingiva and in gingival fluid in patients with periodontitis were indicated." (PMID 40002575, 2025). "Periodontitis is an inflammatory disease which upregulates serum IL-6 levels depending on its severity." (PMID 40894185, 2025). "Chronic periodontitis is known to contribute to systemic inflammation through the release of inflammatory mediators such as interleukin-6 (IL-6) and tumor necrosis factor-alpha (TNF-α), which are also implicated in prostate hyperplasia." (PMID 40004810, 2025). "Beyond bacterial pathogens, the characteristic systemic low-grade inflammatory state of periodontitis elevates circulating levels of C-reactive protein, IL-6 and TNF-α, representing another crucial pathway linking periodontitis to NAFLD." (PMID 40951429, 2025). "IL-6 is another multifunctional cytokine that exerts both local and systemic effects in periodontitis." (PMID 41155385, 2025). "Previous studies have demonstrated an important role for IL-6 in the development of periodontitis, showing elevated levels of this cytokine in the saliva and gingival fluid of patients with periodontitis." (PMID 39458264, 2024).
periodontitis (continued). "The high levels of IL-6 found in patients with periodontitis highlight its important role in the disease's development." (PMID 39044527, 2024). "Elevated levels of cytokines such as interleukin-1β (IL-1β), tumor necrosis factor-alpha (TNF-α), and interleukin-6 (IL-6) are commonly observed in chronic periodontitis." (PMID 38910764, 2024). "The study concludes that strong correlations exist between CRP, LDH, IL-6 levels, periodontitis, and conventional indices in pregnant females, emphasizing the need for early diagnosis." (PMID 38595889, 2024). "Previous studies have shown that in active periodontitis pathology, IL-6 can be secreted by the body’s memory B cells, promoting inflammatory infiltration and facilitating periodontal tissue destruction." (PMID 39830512, 2024). "IL-6 plays a key role in the pathogenesis of periodontitis by inducing osteoclast differentiation and, consequently, bone resorption and inhibiting bone formation." (PMID 39274511, 2024). "IL-6 levels in AD patients were substantially higher than in controls, and periodontitis patients had noticeably higher TNF-a levels than AD patients with healthy periodontium." (PMID 38230738, 2024). "TNF-α, IL-1β, and IL-6 are found in gingival crevicular fluid from pathological gingival pockets seen in periodontitis." (PMID 39258954, 2024). "In saliva, MMP-8 combined with IL-1β, and IL-6, are excellent for detecting periodontitis and identifying non-periodontitis." (PMID 39554809, 2024). "Elevated levels of TNF‐α, IL‐6, and CRP in the plasma of periodontitis patients are closely associated with obesity." (PMID 39675010, 2024). "We observed that IL-6 levels were significantly higher in periodontitis stage III/IV compared to HC (p = 0.003), but also increased in Grade C, albeit without statistical significance, validating, along with other studies, IL-6 importance." (PMID 39125970, 2024). "In experimental models of periodontitis, IL-6 is highly expressed in lesions and several cell types including immune cells and osteoblasts contribute to its production." (PMID 39253090, 2024). "In a recent study assessing GCF cytokine levels in patients with periodontal disease compared to healthy subjects, researchers found significantly higher levels of IL6 in periodontitis patients, as well as IL8, IL12, and IL17." (PMID 38826270, 2024). "Consistent with our results, several studies have revealed increased GCF levels of IL-6 in participants with periodontitis, relative to the levels in healthy controls." (PMID 39215253, 2024). "Obesity is associated with elevated levels of pro-inflammatory cytokines, such as TNF-α and IL-6, which play a role in the pathogenesis of both psoriasis and periodontitis." (PMID 39189252, 2024). "In periodontitis, the upregulation of IL6 and CXCL8/IL8 contributes to tissue destruction and bone resorption, processes that are also regulated during orthodontic tooth movement (OTM)." (PMID 39769290, 2024). "Proinflammatory cytokines, such as IL-1α, IL-1β, IL-6, IL-8, TNF-α and TNF-β, are associated with osteoclastogenesis, a key process leading to clinical periodontitis outcomes and periodontitis-associated inflammatory diseases." (PMID 38396821, 2024). "Consistently, in experimental periodontitis, infection with Porphyromonas gingivalis induced IL-6 levels and consecutive activation of STAT3 and M1-like macrophages." (PMID 39253090, 2024). "It has been suggested that IL-6 activates pro-inflammatory immune circuits in periodontitis by activating innate and adaptive immune cells and by favoring bone resorption together with IL-1 and TNF." (PMID 39253090, 2024). "Among the main inflammatory mediators involved in periodontitis are IL-6 and TNF-α, although other authors also highlight the role of IL-1 and IL-8." (PMID 38396672, 2024). "The results revealed that M. oleifera extract reduced the generation of cytokine IL-6 in patients with periodontitis." (PMID 39445280, 2024).